CREBBP (CREB binding lysine acetyltransferase )
Diseases named in the same sentence as CREBBP in open-access papers (continued):
Sharing a sentence is not in itself a finding about the gene and the disease.
diffuse large B-cell lymphoma (continued). "Mutations in CREBBP, TNFRSF14 and KMT2D predominated in follicular lymphoma, whereas those in BTG2, HTA-A and PIM1 were more frequent in diffuse large B-cell lymphoma." (PMID 33945543, 2021). "Consistently, another study demonstrated that low expression of CREBBP or EP300 inhibits H3K27 acetylation via the FBXW7–NOTCH–CCL2/CSF1 axis to induce the polarisation of tumour-associated macrophages to the M2 phenotype and tumour cell progression in diffuse large B-cell lymphoma (DLBCL)." (PMID 38493218, 2024).
follicular lymphoma (22 papers, 2017 to 2025). Follicular lymphoma is a form of non-Hodgkin lymphoma characterized by a proliferation of B cells whose nodular structure of follicular architecture is preserved. "Approximately 39% of DLBCL and 41% of follicular lymphoma patients contain inactivated mutations in the CREBBP or EP300 genes and are commonly seen in GBC-DLBCL." (PMID 37884941, 2023). "CREBBP mutations were detected in in situ follicular neoplasia, a neoplasm recently reported to preceed follicular lymphoma." (PMID 35795062, 2022). "CLL samples with mutations of the transcriptional cofactor CREBBP, known as a key driver in follicular lymphoma, were more sensitive to the mTOR inhibitor everolimus." (PMID 29227286, 2018). "Overall, the mutation profile of the MYC/BCL2/BCL6-TH group is very similar to that of the MYC/BCL2-DH group, characterised by frequent mutations in follicular lymphoma associated genes (BCL2, CREBBP, KMT2D, EZH2, TNFRSF14)." (PMID 38184753, 2024). "We report herein a novel fusion gene involving CIITA and CREBBP in a patient with a low-grade follicular lymphoma (FL) but with high Ki-67 proliferation index." (PMID 33777766, 2021). "Of these, mutations in CREBBP, KMT2D, TNFRSF14 and RRAGC were enriched in follicular lymphoma, and those of BTG2, HLA-A, PIM1, IGLL5, SOCS1, CD83 and SGK1 were enriched in DLBCL." (PMID 33945543, 2021). "In patients with follicular lymphoma (FL), we, as others, identified frequent mutations in KMT2D, CREBBP, and EZH2 with frequencies of 8/10, 5/10, and 4/10, respectively." (PMID 32013121, 2020). "Recent evidence in follicular lymphoma further demonstrates that activating mutations in STAT6 sensitize tumor cells to IL-4, driving downstream mTOR pathway activation and compensating for CREBBP deficiency." (PMID 40864740, 2025). "In addition, each contingent showed its own pathogenic variants, such as BCL2, KMT2D, EP300 in the follicular lymphoma contingent, and XPO1, TNFAIP3, and CREBBP in the cHL contingent." (PMID 36428786, 2022). "As expected, mutations in frequent drivers such as CREBBP, KMT2D,TNFRSF14 and RRAGC were more frequent among follicular lymphomas, those of MYC, CCND3 and ID3 prevailed among Burkitt lymphoma and those of BTG2, PIM1, SGK1 and SOCS1 were more frequent among DLBCL." (PMID 33945543, 2021). "Histone deacetylase inhibitors (HDACis) have shown promising roles in the treatment of patients with follicular lymphoma (FL), particularly those with nonfunctional CREBBP." (PMID 40426926, 2025). "Recurrent mutations of genes involved in epigenetic regulation (e.g. KMT2D, CREBBP, and EZH2), JAK-STAT pathway (e.g. SOCS1, STAT6), immune signaling (i.e. TNFRSF14), and BCR/NFKB signaling (e.g. CARD11, CD79B) were previously reported in follicular lymphoma cases." (PMID 35795062, 2022).
acute myeloid leukemia (21 papers, 2010 to 2025). Acute myeloid leukemia (AML) is a group of neoplasms arising from precursor cells committed to the myeloid cell-line differentiation. "The interaction between CREBBP and c-Myb regulates HSCs and HSPCs function and is also critical for human acute myeloid leukemia (AML)." (PMID 36831561, 2023). "For GM20199, very little is known, except that its expression dependent on CREBBP in the context of acute myeloid leukemia." (PMID 36386828, 2022). "A CREBBP gene rearrangement with chromosomal translocation has been identified in acute myeloid leukemia and over-expression of CREBBP was found in Jurkat cells." (PMID 21080944, 2010). "The CBP/CREBBP protein is critically involved in embryonic development, growth control, and homeostasis, with CBP/CREBBP gene mutations causing Rubinstein–Taybi syndrome, while chromosomal translocations affecting it are associated with acute myeloid leukemia." (PMID 37509254, 2023). "CREBBP mutations have also been described as an adverse prognostic factor in ALL, acute myeloid leukemia (AML) and follicular lymphoma." (PMID 40393984, 2025). "In addition, several recently developed EP300/CREBBP bromodomain inhibitors have been reported to mediate antiproliferative responses in hematologic cancer cell lines, such as acute myeloid leukemia (AML) and multiple myeloma cell lines and AR-positive prostate cancer cell lines." (PMID 29884215, 2018). "In clinical trials for acute myeloid leukemia, EP300 and CREBBP inhibitors have limited side effects or cytotoxic effects." (PMID 33705753, 2021).
acute lymphoblastic leukemia (18 papers, 2010 to 2025). Leukemia with an acute onset, characterized by the presence of lymphoblasts in the bone marrow and the peripheral blood. "Mutations in the Creb-binding protein gene (CREBBP) are associated with follicular neoplasia and lymphoblastic leukaemia and occasional focal losses and point mutations of the CREBBP gene have been recorded in retinoblastoma tumours." (PMID 33670346, 2021). "Moreover, destruction of the CREBBP really interesting new gene (RING) domain is a recurrent pathogenic event caused by various types of somatic alterations in acute lymphocytic leukemia (ALL)." (PMID 36831561, 2023). "Mutation of CREBBP was described in relapsed acute lymphoblastic leukemia." (PMID 29312619, 2017). "Previous studies on relapsed acute lymphoblastic leukemia (ALL) in pediatric patients identified relapse-specific mutations in CREBBP causing resistance to various drug classes." (PMID 35173708, 2021). "Deletion of CREBBP occurs in 18.3% of patients with acute lymphoblastic leukemia and encodes a transcriptional coactivator and HAT from CREBBP." (PMID 36114448, 2022). "Truncation of CREBBP is acquired in relapsed acute lymphocytic leukemia, further supporting its important role in mediating chemotherapy resistance in lymphoid malignancies." (PMID 31829282, 2019). "Association with poorer outcomes were suggested in studies that found CREBBP mutations in 20% of relapsed/refractory GCB–DLBCL, and in a large proportion of relapsed acute lymphoblastic leukemia patients." (PMID 28302137, 2017).
prostate carcinoma (17 papers, 2010 to 2025). A carcinoma that arises from epithelial cells of the prostate gland. "Similarly, EP300 and CREBBP have been implicated in prostate cancer, with the former identified as an oncogene in a significant proportion of tumors." (PMID 38002524, 2023). "A recent study reported A-485, a new inhibitor selectively targeting histone acetyltransferase (HAT) domain of EP300/CREBBP, showed antitumor effects in several hematologic malignancies and prostate cancer." (PMID 38693103, 2024). "The prostate cancer pathway was chosen to model the AR signaling cascade, containing many of its component genes, such as AR, CREBBP, and PTEN." (PMID 38542265, 2024). "The histone acetyltransferases EP300 and CREBBP are involved in regulation of cellular events in advanced prostate cancer." (PMID 33705753, 2021). "This study investigated the role of EP300/CREBBP inhibitors in enzalutamide-resistant prostate cancer." (PMID 33705753, 2021). "A study reported that miR-N5 targets the 3’-UTR of CREBBP to suppress its expression, which in turn mediates H3K56 acetylation in the promoter regions of EGFR, β-catenin, and CDH1 in prostate cancer." (PMID 38493218, 2024). "Taken together, CREBBP inactivation drives NE features in SCLC and enhances sensitivity to enzalutamide in resistant prostate cancer cells, but its role in NE lineage reprogramming remains unknown." (PMID 39372390, 2024). "EP300 and CREBBP, regulated by way of miR-30a and CREB1, are highly related transcriptional co-activators possessing histone acetyltransferase activity and were known to be involved in the survival and invasion pathways of prostate cancer." (PMID 23282077, 2012).
Intellectual disability (16 papers, 2012 to 2025). "The syndrome, caused by de novo mutations in the CREBBP gene, is characterized by phenotypic variability, including intellectual disability, facial dysmorphisms, and systemic abnormalities." (PMID 40869958, 2025). "The classic phenotype, which caused by deletions or truncating mutations of the CREBBP gene, is characterized by intellectual disability, broad thumbs, and characteristic facial dysmorphism." (PMID 35986282, 2022). "Rubinstein-Taybi syndrome (RSTS) is a rare multisystem developmental disorder with moderate to severe intellectual disability caused by heterozygous mutations of either CREBBP or EP300 genes encoding CBP/p300 chromatin regulators." (PMID 32562237, 2020). "Another brother had a syndrome of kidney failure, intellectual disability, and diabetes mellitus, which seemed to be caused by mutation in the CREBBP gene." (PMID 31870441, 2019). "As compared to patients with the CREBBP gene variant, patients carrying the EP300 gene variant have a relatively milder clinical phenotype, particularly milder skeletal abnormalities of the thumbs and toes and less severe intellectual disability." (PMID 37085840, 2023). "For example, variants in the proximal part of CREBBP lead to the formation of a premature stop codon that may not be associated with severe intellectual disability, which is usually one of the key features of the syndrome." (PMID 39958159, 2025).
bladder cancer (13 papers, 2015 to 2025). "Similarly, CREBBP mutations were a positive prognostic factor in the combined cohort, and were most common in colorectal and bladder cancer patients." (PMID 35798829, 2022). "Mutational status in CREBBP and/or EP300 was associated with improved OS in selected gastrointestinal tumors and bladder cancer." (PMID 41301688, 2025). "The most frequently mutated genes in ordinary bladder cancer are TP53x, KMT2A, SPTAN1, ERBB2, CREBBP, FAT1, ATM, and KMT2C." (PMID 36779496, 2023). "Additionally, the most frequently mutated genes in ordinary bladder cancer are KMT2C, ATM, FAT1, CREBBP, ERBB2, SPTAN1, and KMT2A." (PMID 39399176, 2024).
small cell lung carcinoma (12 papers, 2014 to 2025). Small cell lung cancer (SCLC) is a highly aggressive malignant neoplasm, accounting for 10-15% of lung cancer cases, characterized byrapid growth, and early metastasis. "The CREB binding protein gene (CREBBP) is among the most frequently mutated genes in small-cell lung cancer (SCLC)." (PMID 39858036, 2025). "CREBBP, encoding an acetyltransferase, is one of the most frequently mutated genes in small cell lung cancer." (PMID 36959801, 2023). "Approximately 10–15% of non-small cell lung cancers (NSCLC) and small cell lung cancers (SCLC) have CREBBP loss-of-function mutations." (PMID 31590683, 2019). "For example, genomic alteration of CREBBP is associated with esophageal cancer and small cell lung cancer." (PMID 25915404, 2015). "Loss of CREBBP has been shown to reduce histone acetylation and transcription of cellular adhesion genes in small cell lung cancer, whereas MUC16, which is related to many types of cancers, increases metastasis via modulation of E‐cadherin, N‐cadherin, and vimentin expression." (PMID 38323355, 2024). "CREBBP expression has also been shown to be associated with prognosis of small cell lung cancer." (PMID 25915404, 2015). "Gene Hsa.4937 (CREBBP) acts as a potent tumor suppressor in small cell lung cancer, and inactivation of CREBBP enhances responses to a targeted therapy." (PMID 31150453, 2019). "Recent in-vitro and animal model work in small cell lung cancer has demonstrated that CREBBP mutant tumors may be preferentially sensitive to HDAC1 inhibitors." (PMID 36514795, 2022). "HATs like CREBBP (CREB binding protein) and EP300 were found to be over-expressed in the colon and small cell lung cancers." (PMID 32746900, 2020).
diabetes (11 papers, 2012 to 2024). "The presence of MAPK1/ELK1/CREBBP axis in the core subnetwork and its direct crosstalk to the insulin pathway is consistent with experimental observations that link insulin signaling and diabetes risk to the regulation of learning and formation of long-term memory." (PMID 23885764, 2013).
lung carcinoma (11 papers, 2011 to 2025). "We utilized both HNSCC and lung-cancer cell lines (which also harbor mutations in either CREBBP or EP300)." (PMID 34732714, 2021). "The study found that G1-S phase cell-cycle arrest occurs after inhibition of P300 in CREBBP-deficient or CREBBP-knockdown lung cancer cells." (PMID 31590683, 2019). "CREBBP is a transcriptional co-activator downstream of the TGFβ pathway and the mutations and deletions of the CREBBP gene are associated with lung cancer." (PMID 21211025, 2011). "Interestingly, inactivation of chromatin modifier p300, a homolog of the histone acetyltransferase CREBBP, has been associated with deregulation of MYC transcription in lung cancer cell lines, and loss of MYC expression in the context of CREBBP and EP300 loss is synthetically lethal." (PMID 31097695, 2019). "Similar to HNSCC lines, treatment with A-485 generally led to more profound radiosensitization in CREBBP/EP300 mutant but not wild-type lung-cancer cell lines." (PMID 34732714, 2021). "Additionally, A-485 led to dramatic and significant repression (ranging from 44% to 75% versus control) of HR in CREBBP or EP300 mutant HNSCC and lung-cancer cell lines, but not in wild-type cells." (PMID 34732714, 2021).
autism (10 papers, 2012 to 2025). Persistent deficits in social interaction and communication and interaction as well as a markedly restricted repertoire of activity and interest as well as repetitive patterns of behavior. "In addition, many genome-wide studies including gene association analysis and whole exome sequencing have implicated CREBBP as an autism candidate gene, or interaction hub." (PMID 26730956, 2016). "However, CREBBP has also been associated with primary autism in more than 10 research articles and the SFARI database, suggesting that it could explain the pure ASD clinical presentation in AUT157." (PMID 38003033, 2023). "Menke and Hennekam analyzed 11 patients with CREBBP mutations and 2 with EP300 homologous region variants, who lacked typical RSTS features but exhibited developmental delay, autism-like behaviors, short stature, and microcephaly (DDD study, 2018)." (PMID 40672389, 2025). "CTNNB1 protein and CREB‐binding protein (CREBBP) exist in all autism networks, except for the APPIN2." (PMID 37807632, 2023). "The patient showed all the typical features of Autism, WES revealed a de novo frameshift mutation in CREBBP and de novo sequence variants in TNC and IGFALS genes." (PMID 25768348, 2015). "This gene interaction based evidence for the association of CREBBP with autism genes is not known to have been reported in the literature before." (PMID 23190929, 2012). "Nevertheless, CREBBP is considered an ASD correlated gene in humans and is listed in autism gene databases." (PMID 26730956, 2016).
gastric cancer (10 papers, 2017 to 2025). A primary or metastatic malignant neoplasm involving the stomach. "For example, KAT6A showed a relatively higher mutation frequency in pancreatic and gastric cancers, and the majority of the mutations were missense mutations, whereas CREBBP showed the highest mutation frequency than other genes in gastric and colorectal cancers." (PMID 35422864, 2022). "Moreover, RNF43 and CREBBP mutations have been frequently observed in MSI-H gastric cancer or colorectal cancer, indicating a favorable immune context in these tumors." (PMID 33947957, 2021). "For example, in gastric cancer, DNA damage response induced by oxidative stress can promote the binding of H3K27ac and CREBBP, thus facilitating the expression of lncRNA NORAD." (PMID 37686677, 2023). "The ChIP assay showed that H3K27ac and CREBBP were enriched at the NORAD promoter of both gastric cancer cells and oxaliplatin-resistant cells." (PMID 33462197, 2021). "Similarly, the CREBBP gene was positively correlated with C1GALT1 gene expression levels in all cancer types, including pancreatic cancer, except stomach cancer." (PMID 40548474, 2025).
glioma (10 papers, 2014 to 2026). A benign or malignant brain and spinal cord tumor that arises from glial cells (astrocytes, oligodendrocytes, ependymal cells). "Our analysis implicated CREBBP, a histone acetyltransferase involved in chromatin remodeling, as a novel tumor suppressor in human glioma." (PMID 25423036, 2014). "An additional 509 adult lower grade infiltrating gliomas from the publicly available TCGA dataset were screened for BCOR or CREBBP fusions." (PMID 32493417, 2020). "Circ-CREBBP was reported to be upregulated in gliomas, accelerating the cell proliferation." (PMID 37599427, 2023). "To probe potential downstream biological consequences of BCOR and/or CREBBP alteration, we compared the transcriptional profile of our index case to that of a cohort of 82 samples (over 67 patients) of adult and pediatric infiltrating gliomas for which we had also performed RNAseq." (PMID 32493417, 2020). "Circ-CREBBP regulated the expression of GLS by adsorbing miR-375, accelerating the glutamine metabolism, thus boosting the glioma progress." (PMID 37599427, 2023). "The previously reported events include BCOR-CREBBP and CREBBP-BCOR fusions in ESS, and EP300-BCOR fusions in 3 cases of pediatric glioma." (PMID 32493417, 2020). "Furthermore, we compared the BCOR-CREBBP fusion product in the present case to that of previously reported chimeric transcripts involving BCOR rearrangements with CREBBP or EP300 in ESS and pediatric gliomas." (PMID 32493417, 2020).
Cognitive impairment (8 papers, 2015 to 2023). Abnormal cognition is characterized by deficits in thinking, reasoning, or remembering. "A recent study has shown that hypermethylation at the CREBBP gene is associated with cognitive impairment in 551 participants from Mexican American cohort." (PMID 37373839, 2023). "Moreover, mutations in CREBBP have been associated with cognitive impairment, suggesting its pivotal role in maintaining neuronal health." (PMID 38002524, 2023). "Severe cognitive impairments and autistic features have been reported in patients with large deletions in CREBBP." (PMID 25768348, 2015).
colon carcinoma (8 papers, 2010 to 2025). "Initial work showsthat inhibition of the CREBBP/EP300 bromodomain results in the downregulationof c-Myc in HCT116 colon cancer cells." (PMID 34255515, 2021). "Notably, we observed that mutations in KRAS, PIK3CA, CREBBP, FAT1, PKHD1, ARID2, and POLE were specifically enriched in right-site colon cancers in both our cohort and the validation cohort." (PMID 36439454, 2022). "ICG-001 inhibits CREBBP and was discovered from screening in a colon cancer cell line." (PMID 23408876, 2013). "We have validated at least two examples (CREBBP and EP300) of naturally expressed mutant proteins in MSI-High colon cancer cell lines, both arising from NMD-resistant transcripts." (PMID 21209843, 2010).